RNU6-482P (RNA, U6 small nuclear 482, pseudogene)
Gene: Small nuclear RNA gene on chromosome 5 (112,778,363 to 112,778,469, forward strand). Ensembl gene ENSG00000212370.
Homologues: Orthologues: chimpanzee U6 (96% identical), macaque U6 (95% identical), pig U6 (76% identical), guinea pig U6 (75% identical), mouse Gm55508 (62% identical). Paralogues in human: RNU6-140P (84% identical), RNU6-664P (82% identical), RNU6-86P (82% identical), RNU6-409P (81% identical), RNU6-698P (81% identical), RNU6-726P (81% identical), RNU6-756P (81% identical), RNU6-810P (81% identical), RNU6-1031P (80% identical), RNU6-1145P (80% identical), RNU6-116P (80% identical), RNU6-1175P (80% identical), and 1286 more.